IL1B (interleukin 1 beta)
Diseases named in the same sentence as IL1B in open-access papers (continued):
Sharing a sentence is not in itself a finding about the gene and the disease.
demyelinating disease (17 papers, 2008 to 2025). A broad group of disorders that affect the myelin sheaths that cover the neurons. "In fact, the pro-inflammatory cytokines IL-6 and IL-1β have critical roles in the pathogenic immune responses leading to TMEV-induced demyelinating disease in SJL/J mice." (PMID 35805128, 2022). "IL-6 and IL-1β play particularly important roles in the pathogenic T cell responses in the development of TMEV-induced demyelinating disease." (PMID 34067536, 2021). "We have previously demonstrated that administration of LPS or IL-1β causes resistant C57BL/6 mice to develop demyelinating disease." (PMID 22985464, 2012). "We have previously demonstrated that administration of IL-1β into resistant B6 mice renders the resistant mice susceptible to TMEV-induced demyelinating disease." (PMID 22985464, 2012). "Proinflammatory cytokines, the mediator molecules of inflammation, such as IFN-γ, TNF-α and IL-1β, have been shown to be derived from macrophages/microglia and have been implicated in the pathogenesis of demyelinating diseases." (PMID 18394170, 2008). "Therefore, the excessive production of IL-6 and IL-1β appears to be mainly responsible for the development of demyelinating disease via preferential differentiation of pathogenic Th17 cells." (PMID 34067536, 2021). "Furthermore, we have also utilized IL-1R-deficient mice to investigate the role of IL-1β-mediated signaling in the development of TMEV-induced demyelinating disease." (PMID 22985464, 2012). "Furthermore, the downstream mechanisms associated with the effects of IL-1β on the pathogenesis of virally induced demyelinating disease remain unknown." (PMID 28445497, 2017). "The upregulation of Il1b during the acute attack is a common feature in most demyelinating diseases." (PMID 38216632, 2024). "The treatment of resistant C57BL/6 mice with LPS, a ligand of TLR4, or IL-1β increases the viral load in the CNS and leads to the pathogenesis of demyelinating disease." (PMID 37153539, 2023). "Excessive levels of cytokines, particularly IL-6 and IL-1β, facilitate the generation of pathogenic Th17 immune responses to viral antigens and autoantigens, leading to TMEV-induced demyelinating disease." (PMID 37153539, 2023). "Treatment of resistant B6 mice with LPS, a ligand of TLR4, or IL-1β, caused the mice to develop TMEV-induced demyelinating disease." (PMID 34067536, 2021). "CBD has also been shown to suppress IL-1β production in a mouse viral-induced demyelinating disease model, while reducing vascular activation as determined by monitoring endothelial VCAM-1 expression." (PMID 31681262, 2019). "The role of IL-1β in the pathogenesis of TMEV-induced demyelinating disease was previously investigated." (PMID 28445497, 2017). "We have previously demonstrated that the level of IL-1β plays a pivotal role in the pathogenesis of TMEV-induced demyelinating disease as well as in protection from the disease." (PMID 28445497, 2017). "The presence of TLRs, IL-1β or type I IFNs is necessary for protection from the development of TMEV-induced demyelinating disease, yet excessive signaling through these molecules promotes the development of the disease." (PMID 28445497, 2017). "To further investigate the potential role of IL-1β-mediated signaling in the development of TMEV-induced demyelinating disease, we compared the development of TMEV-induced demyelinating disease in IL-1R KO mice with a B6 background and control B6 mice." (PMID 22985464, 2012). "Administration of IL-1β, thereby rending resistant B6 mice susceptible to TMEV-induced demyelinating disease, induced a high level of Th17 response." (PMID 22985464, 2012). "However, excessive IL-1β administration also exerts pathogenic effects by elevating pathogenic Th17 responses, rendering C57BL/6 mice susceptible to demyelinating disease." (PMID 41214106, 2025).
demyelinating disease (continued). "This is consistent with the fact that TMEV infection and replication are greater in the cells of susceptible mice and that excessive TLR signal and cytokine production, including IL-1β, IL-6, and TGFβ, further promotes the pathogenesis of demyelinating disease." (PMID 37153539, 2023). "In the EAE animal model of MS, IL-1β plays a major role in this demyelinating disease." (PMID 29615953, 2018). "In conclusion, we propose that Th1 cell-derived humoural factors, mainly IFNγ, induce microglial activation and the release of IL-1β that downregulates astrocytic Cx43, which might exacerbate the inflammatory processes in demyelinating disorders." (PMID 27929069, 2016). "Therefore, administration of IL-1β, resulting in a higher level of IL-1β, appears to promote the pathogenesis of TMEV-induced demyelinating disease in resistant B6 mice by elevating pathogenic Th17 and Treg responses to TMEV antigens." (PMID 22985464, 2012). "Thus, the differences in the type and intensity of TLR signals on antigen-presenting cells may affect the levels of viral infection, replication, and production of IL-1β and IL-6, which are critical factors in the development of demyelinating disease." (PMID 37153539, 2023). "In addition, our earlier studies indicated that administration of either lipopolysaccharide (LPS) or IL-1β, thereby inducing high levels of IL-6 production, into resistant C57BL/6 (B6) mice renders the mice susceptible to the development of TMEV-induced demyelinating disease." (PMID 22985464, 2012). "Therefore, functional inhibition of key inflammatory cytokines, such as IL-6, IL-1β, and/or IL-17, which are critical for the development of pathogenic T cell responses and viral persistence, may prevent the pathogenesis of TMEV-induced demyelinating disease." (PMID 34067536, 2021). "We have also reported that TLR3, MDA-5, IL-1β and type I IFNs play critical roles in the development of TMEV-induced demyelinating disease." (PMID 28445497, 2017). "Among the important cytokines, the effects of TNF-α, IL-1β, IL-6, IFN-α/β, and prostaglandin E2, which either alter the type of T cell responses or inhibit immune responses in the development of demyelinating disease, have been investigated." (PMID 33086489, 2020). "Interestingly, the level of IL-1β, induced following infection with TMEV, plays an important role in the pathogenesis of TMEV-induced demyelinating disease." (PMID 22985464, 2012). "Interestingly, serum IL-1β did not correlate with the measure of disease severity in children with acquired demyelinating disorders of the CNS, the prototype of autoimmune neuroinflammation." (PMID 32151248, 2020). "Recently, it was also shown that the presence of FoxP3+ Treg cells that preferentially expand due to stimulation by IL-1β is not beneficial for the development of TMEV-induced demyelinating disease; hence, these regulatory cells inhibit the protective anti-viral immune responses." (PMID 22985464, 2012).
gestational diabetes mellitus (17 papers, 2016 to 2025). "A further study has reported that in vitro treatment using AR-42 enhances the secretion of IL-1β, TNFα and IL-6 in monocytes obtained from patients with gestational diabetes mellitus." (PMID 37728477, 2023). "GSK3β is implicated in inflammatory processes, increasing IL-1β and MCP-1, among other pro-inflammatory cytokines, in the adipose tissue of women with gestational diabetes." (PMID 37108229, 2023). "A mice model of gestational diabetes has also found that inhibiting the IL-1β signaling pathway improves glycemia." (PMID 33774704, 2021). "TNF-α, IL-1β, and IL-6 are essential in early pregnancy, but, with the evolution of gestation, high TNF-α levels can promote preeclampsia and gestational diabetes mellitus, while low IL-10 levels are associated with preterm birth." (PMID 27294162, 2016). "In addition, in pregnant women with gestational diabetes mellitus, SPX showed associations with immunological factor IL1-β and other cardiometabolic factors." (PMID 30254709, 2018). "Crocetin decreased the expression levels of IL-6, TNF-α, and IL-1β, increased the levels of antioxidant enzymes such as SOD, GSH-Px, GSH, and CAT, and increased body weight in rats with STZ-induced gestational diabetes mellitus (GDM)." (PMID 38004168, 2023). "Reduced levels of TNF-α, IL-1β, and IL-6 during KLF9 silencing suggest suppressed inflammation in gestational diabetes mellitus." (PMID 37940560, 2023). "AGEs directly increase IL-1β secretion without lipopolysaccharide priming in human peritoneal macrophages and in adipose tissue of women with gestational diabetes." (PMID 29230270, 2017). "Recent studies indicate that OSA events positively correlate with systemic inflammation in both normal pregnancies and those with gestational diabetes mellitus (GDM), as indicated by higher circulating levels of TNF-α, IL-1β, IL-8, and IL-10." (PMID 38339130, 2024).
keratoconus (17 papers, 2008 to 2025). A degenerative, structural disorder of the eye, characterized by a cone-shaped protrusion of the cornea. "that the IL1B promoter polymorphism, rs1143627, is associated with keratoconus in the Japanese population." (PMID 23592922, 2013). "Statistically significant association was observed for rs1143627 (−31 T>C) in the IL1B promoter region; the T allele of rs1143627 was associated with an increased risk of keratoconus (p=0.014, corrected p value [pc]=0.043, odds ratio=1.38)." (PMID 23592922, 2013). "Here, we report a significant association between IL1B promoter polymorphism rs1143627 and keratoconus in Japanese patients, suggesting that the IL1B promoter polymorphisms contribute to the risk of keratoconus in Japanese and Korean populations." (PMID 23592922, 2013). "Polymorphisms in the interleukin 1 alpha (IL1A) and IL1B gene regions were previously associated with keratoconus in a Korean population." (PMID 23592922, 2013). "The T-C haplotype of IL1B −31 and –511 was more prevalent in keratoconus patients than in control subjects and carried a higher risk of keratoconus (p=0.034, OR=1.58, 95% CI 1.018<2.448)." (PMID 19043479, 2008). "Two IL1B SNPs, −31C/T and −511T/C, have been implicated as potential risk factors for keratoconus among unrelated patients." (PMID 19043479, 2008). "Consequently, polymorphisms, such as those in the IL-1B gene, have been linked to an increased risk of keratoconus." (PMID 40217908, 2025). "In the present study, we investigated whether the IL1A and IL1B polymorphisms are associated with keratoconus in a Japanese population." (PMID 23592922, 2013). "IL1B polymorphisms have conferred modest risk for keratoconus (e.g., OR=1.3–1.5) in the present and previous studies, and therefore, the previous linkage studies may not have been able to find 2q14." (PMID 23592922, 2013). "Thus, IL1B may play an important role in the development of keratoconus through genetic polymorphisms." (PMID 23592922, 2013). "In conclusion, the present study suggests that two SNPs in IL1B predict keratoconus predisposition in unrelated Korean patients, although further research is necessary to elucidate the relationship between the expression levels of IL1α, IL1β, and IL1Ra and SNPs of IL1B in keratoconus patients." (PMID 19043479, 2008). "Significant differences in allelic frequency of IL1B between keratoconus patients and the control group suggest that IL1B polymorphisms may play a role in the susceptibility of unrelated Koreans to develop keratoconus." (PMID 19043479, 2008). "The use of Spearman correlation matrices further revealed stronger and more coordinated cytokine co-regulation in the stable keratoconus group compared to healthy controls, particularly involving IL-6, IL-1β, and TNF-α." (PMID 40980981, 2025). "Stable keratoconus patients displayed stronger positive correlations among multiple cytokines, particularly IL-6, IL-1β, and TNF-α, indicating a more coordinated inflammatory network." (PMID 40980981, 2025). "In our study, we found increased levels of IL-1b in both the keratoconus and the relatives' groups compared to the normal subjects." (PMID 30245588, 2018). "Further genetic and functional studies are needed to clarify the contribution of the IL1B promoter region to the development of keratoconus." (PMID 23592922, 2013). "The T-T haplotype of IL1B −31 and −511 was less frequent in keratoconus patients than in the control individuals (p=0.009), which was associated with protection." (PMID 19043479, 2008). "Variants in this gene can influence the production of interleukin-1 beta, a key pro-inflammatory cytokine that may contribute to the inflammatory processes and up-expression of MMP9 observed in keratoconus." (PMID 40217908, 2025).
keratoconus (continued). "Keratoconus, with a similar inflammatory profile to that of ocular surface disease, has elevated Interleukin (IL)-1β, IL-6, tumor necrosis factor (TNF)-α, and matrix metalloproteinase (MMP)-9, contributing to extracellular matrix degradation and stromal thinning." (PMID 40993744, 2025). "Analyses of tears and corneal tissue in patients with keratoconus have shown an increase in several cytokines, including IL-6, IL-8, IL-1β, TNF-α, and IFN-β, which may support this hypothesis." (PMID 38203537, 2023). "The IL1-B protein has been detected in human corneal epithelial, stromal fibroblast, and endothelial cells, and expression of this protein has reportedly been enhanced in keratoconus corneas compared to normal corneas." (PMID 23592922, 2013). "The goal of this study was to elucidate whether polymorphisms in IL1A, IL1B, and IL1RN are associated with keratoconus in Korean patients." (PMID 19043479, 2008). "Genotype frequencies of IL1A and IL1B in keratoconus patients." (PMID 19043479, 2008). "We investigated the association between IL1A (rs1800587, rs2071376, and rs17561), IL1B (rs1143627, rs16944, rs1143634, and rs1143633), and IL1RN (rs419598, rs423904, rs424078, and rs315952, variable number tandem repeat [VNTR]) polymorphisms in 100 unrelated Korean keratoconus patients." (PMID 19043479, 2008). "For example, concentrations of IL-6, IL-8, IL-1β, and TNF-α are markedly elevated in keratoconus patients relative to healthy controls." (PMID 40547926, 2025). "We observed significantly higher levels of IL-1β, IL-10, IFN-γ and TNF-α in moderate and severe keratoconus than in mild keratoconus (p < 0.05)." (PMID 38256126, 2024). "Interestingly, we observed a significantly higher level of IL-1β, IL-10, IFN-γ, and TNF-α with moderate and severe keratoconus than with mild keratoconus." (PMID 38256126, 2024). "None of the previous linkage studies of keratoconus has ever detected 2q14 locus harboring IL1B." (PMID 23592922, 2013). "Since rs2071376 was not linked with the IL1B SNPs, rs1143627 and rs16944, in the Japanese and Korean populations, the possibility that IL1A SNP rs2071376 is primarily associated with the development of keratoconus is low." (PMID 23592922, 2013). "By correlating corneal and immunological data, we observed significantly higher levels of IL-1β, IL-10, IFN-γ and TNF-α in moderate and severe keratoconus than in mild keratoconus (p < 0.05), but not exceeding the values in the control group." (PMID 38256126, 2024).
Miscarriage (17 papers, 2014 to 2025). A pregnancy that ends at a stage in which the fetus is incapable of surviving on its own, defined as the spontaneous loss of a fetus before the 22th week of pregnancy. "IL-1β can induce an elevation in Th-1 cells, which may be one of the causes of miscarriage induced by IL-1β." (PMID 38362587, 2023). "A previous study revealed that IL-1β was significantly upregulated in the decidua of spontaneous and recurrent miscarriage placentas." (PMID 39992946, 2025). "Significantly higher median concentrations of IL-18 and IL-1β were observed in the sera of women with NET-negative miscarriages as compared to the control values." (PMID 39408839, 2024). "The assessment of placental tissue samples revealed a statistically significant higher expression of IL-1β (p < 0.0001), IL-18 (p < 0.0001), and Caspase-1 (p < 0.0001) proteins in all women with miscarriage as compared to the control group." (PMID 39408839, 2024). "Results showed that miscarriage cases had significantly lower levels of IL-1β, TNF-α, V, Cu, Zn, and Se compared to successful live birth cases." (PMID 39683462, 2024). "In the placental tissue samples, a higher expression of IL-1β, IL-18, and Caspase-1 proteins was noted in women who had experienced miscarriage as compared to the control group." (PMID 39408839, 2024). "The detailed analysis of individual cases revealed that 85% of women with miscarriage showed a strong expression of IL-1β, while 15% showed a weak expression, with 100% showing a weak expression in the control group." (PMID 39408839, 2024). "The concentrations of NLRP3, IL-1β, IL-18, and cytochrome C in the serum of patients after miscarriage were measured by means of the immunoenzymatic method." (PMID 39408839, 2024). "We demonstrated the excessive activation of inflammasome NLRP3, IL-18, and IL-1β in spontaneous miscarriage compared to normal pregnancy." (PMID 35745744, 2022). "There are discrepancies in the literature regarding the role of Il-1β in the pathogenesis of miscarriages." (PMID 34444287, 2021). "Whitcomb tested the serum of women 10 days before miscarriage, and found low levels of several pro-inflammatory cytokines, IL-1β, IL-4, IL-6, IFN-γ and TNF- α, which confirms our findings." (PMID 34300281, 2021). "TNF -238G > A, TNF -308G > A, IL1B -511 T > C, IL1B 3954C > T, IL6 -174G > C, IL6 -634C > G, IL10 -1082A > G and IFNG 874A > T polymorphisms were genotyped on 775 women with idiopathic recurrent miscarriage and 805 healthy parous control women." (PMID 29017513, 2017). "This hypothesis is supported by the high expression of IL-1β and IL-18, along with elevated levels of Caspase-1 in the placenta tissue of women who experienced miscarriage." (PMID 39408839, 2024). "That an interleukin would be important in pregnancy establishment and maintenance is supported by studies on interleukin 1 beta (IL1B), another associated leading edge gene, and interleukin 15 (IL15), for which over-expression leads to miscarriage and implantation failure." (PMID 38927701, 2024). "Additionally, a significant increase in the expression of IL-1β has been reported in the decidua of spontaneous and recurrent miscarriage placentas." (PMID 36362749, 2022). "Finally, we found that DSCs from patients with spontaneous abortion (SA) produce significantly lower levels of G-CSF compared to healthy pregnant women in response to exogenous IL-1β or monocyte-derived DCs." (PMID 33193360, 2020). "In aggregate, attempts to manipulate the GPR124 and inflammasome NLRP3, IL-18, and IL-1β signaling that have a critical role in spontaneous miscarriage may be a way to clarify the actions of mi138-5p in decidual endometrial stromal cells related to embryo implantation and early pregnancy." (PMID 35745744, 2022). "In the miscarriage model, ML345 not only decreased IL-1β levels but also reduced IL-6 and TNF, which are independent of NLRP3." (PMID 41231359, 2025).